USF1 (upstream transcription factor 1)
Diseases named in the same sentence as USF1 in open-access papers (continued):
Sharing a sentence is not in itself a finding about the gene and the disease.
leukemia (4 papers, 2018 to 2023). A malignant (clonal) hematologic disorder, involving hematopoietic stem cells and characterized by the presence of primitive or atypical myeloid or lymphoid cells in the bone marrow and the blood. "For example, USF2 was associated with progression of leukemia through upregulation of HOXA9, but disruption of USF1 alone had minimal effects." (PMID 37515158, 2023). "Similarly, USF1 expression level was positively related with dCK gene, which was a well-documented DS leukemia-related gene." (PMID 29351810, 2018). "Although our study identified the regulatory function of USF1/USF2 on HOXA9 maintenance and leukemia cell survival in MLLr B-ALL and AML cell lines, other HOXA9-independent functions of USF1/2 cannot be excluded and requires further studies." (PMID 33001025, 2020). "Rothem et al26 have reported that reduced expression of transcription factors as CREB1, ATF1, USF1, FOS, JUN, Sp3, and Sp1 is responsible for a major decrease in RFC mRNA expression in the CCRF‐CEM and derived human leukemia cell lines." (PMID 32614991, 2020). "In addition, USF1 and USF2 synergistically regulate HOXA9 expression and leukemia survival in OCI-AML2." (PMID 33001025, 2020). "USF1 and USF2 synergistically regulate HOXA9 expression in MLLr leukemia." (PMID 33001025, 2020).
lung adenocarcinoma (4 papers, 2020 to 2023). A carcinoma that arises from the lung and is characterized by the presence of malignant glandular epithelial cells. "We further revealed that USF1 promoted lung adenocarcinoma progression through the neural signaling pathway (P75NTR, RIPK2, IRAK1, TRAF5 and IKKβ axis)." (PMID 35155573, 2022). "Moreover, according to the online cancer transcriptome database Oncomine, USF1 and FAK were found to be overexpressed in both lung adenocarcinoma and lung squamous cell carcinoma patients." (PMID 32144580, 2020).
thyroid cancer (4 papers, 2009 to 2017). "On this regard, it has been reported that the rs1867277A allele recruits the USF1/USF2 transcription factors and has been shown to be involved in an allele-specific transcriptional regulation of FOXE1 in thyroid cancer." (PMID 28928994, 2017).
coronary atherosclerosis (3 papers, 2013 to 2018). Atherosclerosis of the coronary vasculature. "In the autopsy series of 700 Finnish middle-aged men, USF1 polymorphisms were analyzed with quantitative morphometric measurements of coronary atherosclerosis." (PMID 26068452, 2015). "The upstream stimulatory factor 1 (USF1) was originally associated with familial combined hyperlipidemia with subsequent associations with lipid levels, coronary atherosclerosis, and acute cardiovascular events." (PMID 30545366, 2018).
cutaneous squamous cell carcinoma (3 papers, 2019 to 2025). "The up-regulation of LINC01048 induced by USF1 promotes cell proliferation and apoptosis in cutaneous squamous cell carcinoma by binding to TAF15 to activate YAP1 transcription." (PMID 32776110, 2020).
Hepatic steatosis (3 papers, 2021 to 2024). Steatosis is a term used to denote lipid accumulation within hepatocytes. "As such, the aggravated liver steatosis phenotype can theoretically explain why bone marrow USF1 deficiency was associated with a rise in the blood concentration of pro-inflammatory monocytes and neutrophils." (PMID 34385562, 2021).
osteosarcoma (3 papers, 2020 to 2025). A usually aggressive malignant bone-forming mesenchymal neoplasm, predominantly affecting adolescents and young adults. "For example, USF1 transcriptionally regulated GAS6-AS2 expression to promote the proliferation, migration and invasion of osteosarcoma cells." (PMID 35155573, 2022).
viral infection (3 papers, 2010 to 2022). "In addition, the same study documents that under acute stress or viral infection USF1 undergoes phosphorylation-dependent acetylation, a modification which negatively affects transcription." (PMID 21050451, 2010). "Moreover, our data may suggest that the presence of methylated E-Box in HeyL promoter may interfere with the binding of USF-1, subsequently impairing its regulatory action on the lung-specific glycoprotein, inflammatory process, and the pulmonary epithelium, especially, during viral infection." (PMID 35655915, 2022).
Combined hyperlipidemia (2 papers, 2021 to 2025). "Upstream stimulatory factor 1 (USF1) is a transcription factor associated with familial combined hyperlipidemia and CAD." (PMID 39759113, 2025).
depression (2 papers, 2022 to 2024). "Confirming our expectation, we found a significant reduction of depression-like and anxiety-like behaviours in USF-1 KO mice of both sexes." (PMID 36450713, 2022). "We used upstream stimulatory factor 1 (USF-1) knock-out (KO) mice as a genetic model of constitutively activated BAT and positive cardiometabolic traits and found a reduction of depression-like and anxiety-like behaviours associated with USF-1 deficiency." (PMID 36450713, 2022). "In light of the strong experimental evidence linking adult hippocampal neurogenesis with depression and the effects of antidepressant treatments, we challenged USF-1 KO and WT mice with BrDU." (PMID 36450713, 2022). "In summary, the findings of the present study identify USF-1 as a positive regulator of cardiometabolic health and behavioural functions related to active stress coping and depression-like behaviour, with a direct impact on the molecular and structural architecture of the brain." (PMID 36450713, 2022). "We then used adult female and male USF-1 KO and WT controls for a comprehensive behavioural characterisation in a battery of standard paradigms, with special emphasis on tests assessing emotional behaviours relevant to depression and anxiety." (PMID 36450713, 2022). "We therefore sought to examine whether the reduction of depression-like and anxiety-like behaviour in USF-1 KO mice was also reflected in an alteration of adult hippocampal neurogenesis." (PMID 36450713, 2022). "Similarly, motor coordination was unaltered in female and male KO mice as determined by the latency to fall in the RR, jointly dismissing unspecific biases through general behavioural alterations on the performance of USF-1 KO mice in the depression-related and anxiety-related tests." (PMID 36450713, 2022). "We show that mice lacking USF-1 display a reduction of depression-like and anxiety-like behaviours in comparison to wildtype (WT) littermates, which persist even after bilateral removal of interscapular BAT depots (iBATx)." (PMID 36450713, 2022). "The decrease in depression-like and anxiety-like behaviours in USF-1 KO mice is not paralleled by a modification of adult hippocampal neurogenesis, but by altered expression of molecular regulators of neuronal morphology and structural adaptations in hippocampal neurons." (PMID 36450713, 2022).
Glomerular sclerosis (2 papers, 2020 to 2021). Accumulation of scar tissue within the glomerulus. "These conditions stimulate transcription factors USF1/2, AP-1 and CREB that activate several genes to accumulate ECM, and which induce inflammation and glomerulosclerosis in the kidney." (PMID 32093382, 2020).
Hyperglycemia (2 papers, 2020 to 2021). An increased concentration of glucose in the blood. "According to a previous study, increased amounts of USF1 and USF2 are bound to the endogenous TSP-1 promoter (-1172 to -878) to regulate hyperglycemia-induced TSP-1 expression." (PMID 32626782, 2020).
liver cancer (2 papers, 2014 to 2022). An epithelial or non-epithelial malignant neoplasm that arises from the liver. "USF1 expression was found to be significantly higher in liver cancer tissue compared with normal liver cancer tissue." (PMID 34996354, 2022). "As a member of c-Myc related family, USF1 could regulate numerous gene expression, which leads to liver cancer progression." (PMID 34996354, 2022). "HepG2 cell line is a liver cancer cell line where CEPB, REST and USF1 strongly contribute to chromatin accessibility." (PMID 34996354, 2022).
lymphoma (2 papers, 2012 to 2025). A malignant (clonal) proliferation of B- lymphocytes or T- lymphocytes which involves the lymph nodes, bone marrow and/or extranodal sites.
myocardial infarction (2 papers, 2006 to 2010). Gross necrosis of the myocardium, as a result of interruption of the blood supply to the area, as in coronary thrombosis. "Third, two other transcription factors have been implicated in cardiovascular phenotypes, MEF2A (myocardial infarction) and USF1 (lipid traits)." (PMID 16934006, 2006).
triple-negative breast carcinoma (2 papers, 2023 to 2024). An invasive breast carcinoma which is negative for expression of estrogen receptor (ER), progesterone receptor (PR), and human epidermal growth factor receptor 2 (HER2). "CircANKS1B was upregulated in triple-negative breast cancer and acted as a miR-148a-3p and miR-152-3p sponge to increase the expression of transcription factors USF1 and TGF-β1 to activate the TGF-β1/Smad signaling pathway and epithelial-to-mesenchymal transition (EMT)." (PMID 39519039, 2024). "In triple negative breast cancer (TNBC), circANKS1B interacts with miR-148a-3p and miR-152-3p, thus increasing the expression of upstream transcription factor 1 (USF1), which then binds TGF-β1120." (PMID 36861443, 2023).
Alzheimer disease (1 paper, 2022). A progressive, neurodegenerative disease characterized by loss of function and death of nerve cells in several areas of the brain leading to loss of cognitive function such as memory and language. "USF1 and USF2 generally exert activating effects, with USF1 being a risk gene for Alzheimer’s disease and relevant for brain cholesterol metabolism involving its transport from astrocytes to neurons." (PMID 35886042, 2022).
Anxiety (1 paper, 2022). Intense feelings of nervousness, tension, or panic often arise in response to interpersonal stresses. "Here, a significant main effect of genotype was noted with female and male USF-1-deficient mice displaying less anxiety face to the more aversive illuminated arms than WT littermates (F = 8.734; p = 0.0045; n = 13–17/group)." (PMID 36450713, 2022).
cholangiocarcinoma (1 paper, 2019). A carcinoma that arises from the intrahepatic biliary tree (intrahepatic cholangiocarcinoma) or from the junction, or adjacent to the junction, of the right and left hepatic ducts (hilar cholangiocarcinoma). "In conclusion, the results presented that overexpressed ZFAS1 is associated with dismal prognosis for cholangiocarcinoma patients and this aberrant modulates proliferation and metastasis via miR‐296‐5p/USF1, which might activate oncogenes expression." (PMID 31565837, 2019). "In conclusion, ZFAS1 might promote cholangiocarcinoma proliferation and metastasis by modulating USF1 via miR‐296‐5p." (PMID 31565837, 2019).
colon adenocarcinoma (1 paper, 2010). "The influence of these TFs upon UGT1A1 transcriptional activity was then demonstrated by transient transfection in colon adenocarcinoma cell line HT29, and solely HNF1-alpha and USF1/2 have been shown to have significant impact." (PMID 20096102, 2010).
colorectal cancer (1 paper, 2025). A primary or metastatic malignant neoplasm that affects the colon or rectum. "In colorectal cancer, dual specificity protein phosphatase 18 (DUSP18) dephosphorylates and stabilizes the upstream stimulatory factor 1 (USF1) transcription factor, which subsequently induces the expression of the SREBF2 gene." (PMID 40270603, 2025).
diabetic nephropathy (1 paper, 2021). "We created diabetic rats with the injection of STZ and examined the pharmacological effects of USF1 PI polyamide-3 on the pathogenesis of diabetic nephropathy." (PMID 33947045, 2021). "It has been reported that USF1 is stimulated through the protein kinase-C/polyol pathway induced by high glucose in diabetic nephropathy." (PMID 33947045, 2021). "We also examined the effects of USF1 PI polyamide on diabetic nephropathy." (PMID 33947045, 2021). "We therefore used USF1 PI polyamide-3 as the lead compound in the following in vitro and in vivo experiments to examine the effects of USF1 PI polyamide on the pathogenesis of diabetic nephropathy." (PMID 33947045, 2021). "Administration of USF1 PI polyamide will prevent the binding of USF1 on TGF-β1 and osteopontin promoters to reduce the pathogenesis of diabetic nephropathy." (PMID 33947045, 2021).
endometriosis (1 paper, 2015). The growth of functional endometrial tissue in anatomic sites outside the uterine body. "Although two types of USF, USF1 and USF2, have been reported, it is USF2 that shows the highest binding activity on SF-1 promoter and its knockdown results in down-regulation of SF-1 and also of its target gene CYP19A1 in ectopic endometrium from endometriosis women." (PMID 26453052, 2015).
familial hyperlipidemia (1 paper, 2021). An instance of hyperlipidemia (disease) that is caused by an inherited modification of the individual's genome. "It has been shown that the mammalian Target of Rapamycin (mTOR) complex phosphorylates JMJD1C, allowing interaction with upstream stimulatory factor 1 (USF1), a molecule that activates lipogenic genes and is associated with familial hyperlipidemia." (PMID 35087844, 2021).
head and neck cancer (1 paper, 2013). A primary or metastatic malignant neoplasm affecting the head and neck. "Consistent with a positive role in tumor progression, expression of the short LAMA3 isoforms, which is multiply controlled by the transcriptional co-activator EP300, along with the transcription factors AP-1, CREB1 and USF1, is increased and portends a dismal prognosis in head and neck cancers." (PMID 24324612, 2013).
HIV-1 infection (1 paper, 2023). The type species of lentivirus and the etiologic agent of acquired immunodeficiency syndrome (AIDS). "The USF2 gene knockout limited T cell activation to a greater extent than the USF1 knockout, and additionally rendered T cells more restrictive to HIV-1 infection." (PMID 37515158, 2023). "As HIV-1 favors the infection of stimulated T cells, and that the loss of USF1 and USF2 dampens T cell activation, we sought to examine the role of these factors for HIV-1 infection." (PMID 37515158, 2023). "However, after 4 days of infection, the USF2 knockout cells accumulated latent HIV-1 infections at a higher proportion compared to the WT or USF1 KO cells." (PMID 37515158, 2023).
Hypertension (1 paper, 2013). The presence of chronic increased pressure in the systemic arterial system. "Recently, the E-boxes in the promoter regions of renin and angiotensinogen were shown to be direct targets of Usf1 and Usf2 and suggested to be involved in the pathogenesis of both hypertension and renal injury." (PMID 23653383, 2013).
ischemic stroke (1 paper, 2025). A stroke disorder caused by obstruction of blood flow to the brain, due to thrombotic (local blood clot formation) or embolic (due to a blood clot or other material traveling from another site) event. "A study by Wang (2013) linked USF1 polymorphisms to the total area of unstable carotid plaques in ischemic stroke patients, while Niemiec (2015) showed that rs2516839 modulates serum triglyceride levels in response to smoking." (PMID 40507612, 2025).
liver cirrhosis (1 paper, 2014). "USF1 and USF2 protein expressions were significantly increased in patients with liver cirrhosis, worse tissue differentiation, advanced HCC stages, high-tendency to metastatic recurrence and postoperative metastatic recurrence (P < 0.05)." (PMID 25149140, 2014). "USF1 and USF2 expressions were increased in patients with liver cirrhosis, worse tissue differentiation, advanced HCC stages and metastatic recurrence." (PMID 25149140, 2014). "Furthermore, we also found that both USF1 and USF2 expressions were significantly increased in patients with liver cirrhosis, poor differentiation, advanced tumor stages, the high-tendency to metastatic recurrence and postoperative metastatic recurrence." (PMID 25149140, 2014).
liver disease (1 paper, 2013). "We therefore decided to study the role of USF1 and three histone modifications in the liver disease ASH." (PMID 24206787, 2013).
liver fibrosis (1 paper, 2012). "USF1 resulted down-expressed during the progression of liver fibrosis in CHC patients and this explains the lower ghrelin expression in CHC patients in respect to those with T2D." (PMID 22745767, 2012).
myocardial ischemia (1 paper, 2025). A disorder of cardiac function caused by insufficient blood flow to the muscle tissue of the heart. "I/R-induced downregulation of Seipin is attributed to the reduced expression of its transcription factor USF1, which is required for metabolic adaptation in acute myocardial ischemia." (PMID 41255216, 2025).
neuroendocrine tumors (1 paper, 2022). "In fact, USF1/2 is reported to bind to COX‐2 E‐box in gastroenteropancreatic neuroendocrine tumors." (PMID 34533293, 2022).
pancreatic cancer (1 paper, 2021). "However, there are few reports on how USF1 modulates the progression of pancreatic cancer, and further studies are needed." (PMID 34290570, 2021).
preeclampsia (1 paper, 2025). Preeclampsia is a hypertensive disorder of pregnancy that is characterized by new-onset hypertension with proteinuria presenting after 20 weeks of gestation, and depending on mild or severe forms may initially present with severe headache, visual disturbances, and hyperreflexia. "Another study demonstrated that the risk alleles of the USF1 gene are predictive of both cardiovascular disease and severe preeclampsia development during pregnancy." (PMID 40507612, 2025).
psoriasis (1 paper, 2021). An autoimmune condition characterized by red, well-delineated plaques with silvery scales that are usually on the extensor surfaces and scalp. "USF1 mRNA expression level in lesional skin of psoriasis patients was 3.0-fold lower (p< 0.01) and in non-lesional skin it was 2.5-fold lower (p < 0.01) than in the skin of healthy controls." (PMID 34884858, 2021). "In psoriasis involved skin, statistically significant positive correlations were found between the expression levels of PNOC and USF1 (r = 0.58, p < 0.05), PNOC and ICAM1 (r = 0.59, p < 0.05) and USF1 and ICAM1 (r = 0.51, p < 0.05)." (PMID 34884858, 2021). "In psoriasis uninvolved skin, positive correlations were found between the expression levels of CREB1 and LEF1 (r = 0.66, p < 0.05), USF1 and PNOC (r = 0.81, p < 0.05), MITF and ATRN (r = 0.58, p < 0.05), MITF and NURR1 (r = 0.56, p < 0.05) and MITF and MAPK14 (r = 0.75, p < 0.01)." (PMID 34884858, 2021).
schizophrenia (1 paper, 2022). A major psychotic disorder characterized by abnormalities in the perception or expression of reality. "Genetic risk factors that overlap with TF-binding sites for USF1, NFIC, and POLR2A have been identified in relation to schizophrenia and MDD." (PMID 36386175, 2022).
squamous carcinoma (1 paper, 2021). "The expression level of LINC010148 can be elevated by USF1, and LINC010148 interacts with TAF15 to bind to the promoter of YAP1, which further triggers the development of squamous carcinoma." (PMID 34285657, 2021).
Ureteral obstruction (1 paper, 2013). Obstruction of the flow of urine through the ureter. "Furthermore, the results of siRNA transfection in mouse distal convoluted tubule cells and those of unilateral ureteral obstruction in the afflicted mouse kidney suggest that Usf1 decreases but Usf2 increases the Agtrap gene expression by binding to the E-box." (PMID 23653383, 2013).